Y_RNA (Y RNA )
Gene: Miscellaneous RNA gene on chromosome 8 (65,592,731 to 65,592,820, forward strand). Ensembl gene ENSG00000200714.
Homologues: Orthologues: chimpanzee Y_RNA (100% identical). Paralogues in human: Y_RNA (91% identical), RNY3 (90% identical), Y_RNA (90% identical), RNY3P1 (89% identical), Y_RNA (89% identical), Y_RNA (88% identical), Y_RNA (87% identical), Y_RNA (86% identical), Y_RNA (84% identical), RNY3P11 (83% identical), Y_RNA (83% identical), RNY3P10 (82% identical), and 94 more.